FABP2 (fatty acid binding protein 2)
Description:
FABPs are thought to play a role in the intracellular transport of long-chain fatty acids and their acyl-CoA esters. FABP2 is probably involved in triglyceride-rich lipoprotein synthesis. Binds saturated long-chain fatty acids with a high affinity, but binds with a lower affinity to unsaturated long-chain fatty acids. FABP2 may also help maintain energy homeostasis by functioning as a lipid sensor.
Synonyms: I-FABP; FABPI
Tractability: Small molecule: a structure with a bound ligand is known; it has a binding pocket of medium quality; it belongs to a druggable protein family. Antibody: the Human Protein Atlas places it where antibodies can reach. PROTAC: a small molecule that binds it is known.
Target class: Fatty acid binding protein family; Auxiliary transport protein
Gene: Protein-coding gene on chromosome 4 (119,317,250 to 119,322,138, reverse strand). Ensembl gene ENSG00000145384.
Subcellular location: Cytoplasm
Subcellular location (Human Protein Atlas): Actin filaments; Cytosol; Plasma membrane
Pathways (Reactome):
Metabolism: Triglyceride catabolism
Gene Ontology:
Molecular function: long-chain fatty acid binding; protein binding; fatty acid binding; lipid transporter activity; lipid binding; long-chain fatty acid transmembrane transporter activity
Biological process: intestinal lipid absorption; fatty acid transport; triglyceride catabolic process; fatty acid metabolic process; intestinal absorption; long-chain fatty acid transport
Cellular component: cytosol; nucleus; apical cortex; cytoplasm; microvillus
Genetic constraint (gnomAD): Loss-of-function variants: 3 observed, 5.71 expected, observed/expected ratio (o/e) 0.53, 90% interval 0.24 to 1.34. That is too few expected variants to judge how well the gene tolerates losing a copy. Missense variants: 96 observed, 94.15 expected, observed/expected ratio (o/e) 1.02, 90% interval 0.86 to 1.21. Synonymous variants: 28 observed, 31.1 expected, observed/expected ratio (o/e) 0.9, 90% interval 0.67 to 1.23.
Homologues: Orthologues: chimpanzee FABP2 (97% identical), macaque FABP2 (95% identical), pig FABP2 (86% identical), rabbit FABP2 (84% identical), rat Fabp2 (82% identical), dog FABP2 (80% identical), mouse Fabp2 (78% identical), guinea pig FABP2 (76% identical), tropical clawed frog fabp2 (71% identical), zebrafish fabp2 (67% identical), Caenorhabditis elegans lbp-7 (23% identical), Caenorhabditis elegans lbp-8 (19% identical). Paralogues in human: CRABP1 (34% identical), CRABP2 (30% identical), FABP4 (30% identical), FABP7 (30% identical), FABP3 (30% identical), RBP1 (28% identical), PMP2 (27% identical), FABP9 (26% identical), RBP2 (25% identical), FABP6 (24% identical), RBP7 (23% identical), FABP12 (22% identical), and 3 more.
Diseases named in the same sentence as FABP2 in open-access papers:
FABP2 is named in the same sentence as 209 diseases in open-access papers, as found by Europe PMC text mining. Sharing a sentence is not in itself a finding about the gene and the disease. The quoted sentences say what the papers report.
Obesity (36 papers, 2012 to 2026). Accumulation of substantial excess body fat. "Specifically, several obesity-related genes, such as fatty acid binding protein 2 (FABP2) and FABP5, exhibited a loss of m6Am in their mRNAs, leading to a significant downregulation of protein expression due to the overexpression of FTO under HFD conditions." (PMID 38509021, 2024). "Several studies have reported that polymorphisms of FABP2 are correlated with an increase in obesity, TD2M and metabolic syndrome onset." (PMID 35887100, 2022). "In light of the evidence that the missense variation is strongly associated with lipid and carbohydrate metabolism, FABP2 is an extensively studied candidate gene related to metabolic disorders including obesity, diabetes, and metabolic syndrome." (PMID 34206471, 2021). "One of the proposed genes associated with obesity, and with potential significance on the body’s adaptive response to training in healthy individuals, is FABP2." (PMID 34206471, 2021). "The FABP2 variant Ala54Thr FABP2 increases the risk of colon cancer development in patients with pronounced hyperinsulinemia and obesity, but, for this to happen, coincidence with other risk factors seems necessary." (PMID 32856199, 2020). "In particular, FTO and FABP2 gene polymorphisms were significantly associated with susceptibility to MS and obesity in this cohort." (PMID 28738793, 2017). "Several studies have found possible association of Ala54Thr polymorphism of the fatty acid binding protein 2 (FABP2) gene with insulin resistance, dyslipidemia and obesity." (PMID 28890888, 2017). "Although little is known about the function of FABP2 in the liver, there is evidence that Ala54Thr polymorphism of FABP2 gene has a role in insulin resistance and obesity." (PMID 23476706, 2013). "Specifically, functional investigations for FABP2 have focused on the intestinal tissues, noting specific polymorphisms in this genes sequence are correlated with obesity and insulin resistance in vertebrates." (PMID 23036107, 2012). "FABP2 transports fatty acids into intestinal epithelial cells to synthesize triglycerides, and its over expression will increase the transport of fatty acids and cause diseases such as dyslipidemia and obesity." (PMID 41376058, 2025). "We argued that HFD induced obesity and associated gut microbiota alteration might cause intestinal damage leading to increased gut permeability and FABP2 expression levels in systemic circulation." (PMID 36164343, 2022). "Our results confirm that the FABP2 Ala54Thr polymorphism may help identify Caucasian participants at risk for obesity." (PMID 34206471, 2021). "We confirm that the FABP2 Ala54Thr polymorphism may help identify women at risk for overweight and obesity." (PMID 34206471, 2021). "FABP4 and FABP2 have recently been reported to have a significant association with cancer progression in patients with colorectal cancer and several studies demonstrate that obesity and high fat intake are risk factors in colorectal cancer." (PMID 32209538, 2020). "In addition, the Ala54Thr polymorphism of FABP2 is also associated with fasting hypertriglyceridemia and obesity." (PMID 30217061, 2018). "Ala54Thr variant allele of FABP2 gene might influence metabolic rate of individual thus gives an impact on obesity risk." (PMID 27127449, 2016). "Carriers of the Thr54 allele in FABP2 gene have a twofold greater affinity for the absorption of long-chain fatty acids than those with the Ala54 allele, which supports the role of the FABP2 Ala54Thr polymorphism in the etiology of obesity and metabolic disorders." (PMID 25606413, 2014). "A polymorphism in FABP2, an alanine-to-threonine substitution at codon 54 (Thr-54), has been reported to be associated with insulin resistance in Pima Indians, a population with an extremely high prevalence of obesity and type 2 diabetes." (PMID 24278421, 2013).
Obesity (continued). "The functional FABP2 Ala54Thr polymorphism (rs1799883) is strongly associated with lipid and carbohydrate metabolism, although the function of its potential modifying effect on training-induced changes in obesity-related parameters is still unknown." (PMID 34206471, 2021). "HFD-induced obesity in mice leads to increased FTO levels and loss of m6Am at specific targets such as Fabp2 and Fabp5 mRNAs." (PMID 40862085, 2025). "For example, two obesity-related fatty acid-binding proteins, FABP2 and FABP5, which lost their m6Am under HFD were both significantly downregulated at the protein levels, while Fabp5 also displayed >10-fold downregulation at the mRNA level as well." (PMID 34893620, 2021). "We find that FTO levels are elevated in fat mice, and that genes which lost m6Am marking under obesity are overly downregulated, including the two fatty-acid-binding proteins FABP2, and FABP5." (PMID 34893620, 2021). "Other candidate genes in association with T2DM include PPARγ, ACE (angiotensin converting enzyme), MTHFR (methylene tetrahydrofolate reductase), FABP2 (fatty acid binding protein-2), and FTO (fat mass and obesity associated gene)." (PMID 26587547, 2015). "A54T polymorphism in FABP2 was investigated as a possible genetic factor associated with T2DM and Obesity." (PMID 24690233, 2014). "Larger studies focusing on analysis of FABP2 in patients with 2DM and obesity will augment our preliminary results." (PMID 22697793, 2012). "The sequences of four so-called obesity genes were gathered and analyzed, including FTO (fat mass and obesity-associated protein), PPARG (peroxisome proliferator-activated receptor), ADRB3 (adrenergic receptor 3), and FABP2 (fatty acid-binding protein 2)." (PMID 36717943, 2023). "Thus, this study aimed to examine the associations between FTO (rs9939609), FABP2 (rs1799883), LEP (rs2167270), LEPR (rs1137101), and MC4R (rs17782313) polymorphisms and obesity-related traits." (PMID 35627568, 2022). "In our study, we also observed an increase in villus domain length and an altered pattern of FABP-2 cell localization in intestinal organoids exposed to palmitate according to previous data observed in villi and enterocytes isolated from obesity and prediabetes mice." (PMID 35887100, 2022). "Therefore, this study aimed to analyze associations between FTO (rs9939609), FABP2 (rs1799883), and LEP (rs2167270), LEPR (rs1137101), and MC4R (rs17782313) polymorphisms and obesity-related parameters." (PMID 35627568, 2022). "In addition, the identification of lean-specific m6Am-methylated key metabolic genes (including Fabp2, and Fabp5) further support m6Am function in the dynamic regulation of obesity." (PMID 34893620, 2021). "Furthermore, polymorphisms in the FTO gene were associated with increased obesity risk, whereas polymorphisms in the FTO and FABP2 genes were also associated with the risk of developing MS in general unmatched cohorts." (PMID 28738793, 2017). "Moreover, “rs1799883” SNP of the fatty acid binding protein 2 (FABP2) gene was found to be associated with hypertriglyceridemia, while “rs9939609” SNP of the fat mass and obesity-associated (FTO) gene was correlated with an increased risk of body fat accumulation." (PMID 38474710, 2024). "Although SNPs were located on obesity-related genes, some of the genes also have a direct role in lipid metabolism including PPARG, FABP2, PLIN1, NPC1, ACSL5, and FAAH, suggesting relationships between genetics, adiposity, and plasma lipid profiles." (PMID 30581838, 2018). "Role of FABP2 in intestinal barrier dysfunction in the case of obesity induced EAE severity is not known." (PMID 36164343, 2022). "Our findings are consistent with Han (2013), who described that 12-week regular aerobic exercise training may beneficially prevent obesity-related traits; however, none of the examined parameters changed significantly across the FABP2 genotypes." (PMID 34206471, 2021).
Obesity (continued). "Although FABP2 chaperonopathy is not firmly established as a carcinogenic factor in patients with colon cancer and hyperinsulinemia and obesity, this issue deserves further investigation, considering the possibility of applying chaperonotherapy to treat these very sick patients." (PMID 32856199, 2020).
celiac disease (26 papers, 2014 to 2025). An autoimmune genetic disorder with an unknown pattern of inheritance that primarily affects the digestive tract. "Finally, a recent multicenter study confirmed that NCGS is affected by an epithelial damage and an impairment in mucosal barrier similar to celiac disease, corroborated by increased levels of fatty acid-binding protein 2 and enhanced permeability." (PMID 29362561, 2017).
Insulin resistance (23 papers, 2012 to 2026). Increased resistance towards insulin, that is, diminished effectiveness of insulin in reducing blood glucose levels. "The Thr54 isoform (T allele) of FABP2 rs1799883 has been associated with hypertriglyceridemia, and increased body mass index (BMI), hyperinsulinemia, and insulin resistance." (PMID 35387194, 2022). "The FABP2 gene has been proposed as a candidate gene for the development of diabetes and insulin resistance because the encoded protein is involved in the absorption and metabolism of fatty acids." (PMID 30217061, 2018). "Further, FABP2 Ala54Thr polymorphism, a mutant phenotype, is closely related to insulin resistance and abnormal lipid metabolism, which are the main risk factors for cardiovascular disease." (PMID 29678171, 2018). "Several studies in mammals associated FABP2 expression or genetic variants to insulin resistance and type 2 diabetes in individuals fed different sources of MCFAs or LCFAs." (PMID 29226031, 2017). "They found that FABP2 Ala54Thr polymorphism was weakly associated with a higher degree of insulin resistance, higher level of fasting insulin and higher level of 2-h BG." (PMID 25388378, 2014). "Numerous studies have assessed FABP2 gene variants and their association with insulin resistance and T2DM." (PMID 25388378, 2014). "In Pima Indians, FABP2 Ala54Thr genotypes was shown to be associated with increased fatty acid-binding, increased fat oxidation, and insulin resistance." (PMID 25388378, 2014). "The FABP2 gene has been proposed as a candidate gene for diabetes and insulin resistance because the protein it encodes is involved in fatty acid absorption and metabolism." (PMID 25388378, 2014). "The intestinal fatty acid-binding protein (FABP2) gene located at chromosome 4q28-31 is a candidate gene possibly implicated in insulin resistance and the pathogenesis of type 2 diabetes mellitus." (PMID 25606413, 2014). "Molecular scanning of FABP2 identified a missense mutation (Ala54Thr) responsible for insulin resistance." (PMID 24156506, 2013). "Contradictory to it, several studies have reported the association between the Ala54Thr polymorphism of FABP2 with insulin resistance and T2DM." (PMID 24156506, 2013). "Furthermore, in 3 of 4 studies in Japanese found an association of decreased insulin resistance with the FABP2 Thr54 allele." (PMID 23826253, 2013). "For instance, the FABP2 gene, encoding the fatty acid-binding protein 2 (FABP2), demonstrates a crucial role in the uptake, transport, and regulation of fatty acids, with polymorphisms in this gene linked to insulin resistance a well-established CRC risk factor in Han Chinese populations." (PMID 39242607, 2024). "In the search for T2DM loci in Pima Indians, Prochazka and co-workers found linkage between insulin resistance and a region on chromosome 4q near the FABP2 locus." (PMID 24156506, 2013). "FABP2 and FATP4 represented long-chain fatty acid uptake and intracellular trafficking, processes linked to intestinal barrier function, systemic inflammation, and insulin resistance." (PMID 41566055, 2026). "As insulin resistance (IR) is an established risk factor for colorectal cancer (CRC), we explored the association between each of the IR-related gene polymorphisms of adiponectin (ADIPOQ) rs2241766, uncoupling protein 2 (UCP2) rs659366, and fatty acid-binding protein (FABP2) rs1799883 and CRC risk." (PMID 23826253, 2013). "Meanwhile, others have reported that the production of I-FABP was determined partly by duodenal FABP2 gene expression, but its serum concentration was affected by BMI and insulin resistance." (PMID 36701395, 2023). "In parallel, FABP2 and FATP4 mediate dietary fatty acid absorption and intracellular trafficking, and disruption of these proteins contributes to systemic inflammation, lipid malabsorption, and insulin resistance." (PMID 41566055, 2026).
Insulin resistance (continued). "Thus, it remains to be established if this model can be assessed for the development of insulin resistance by studying GLUT4 transport at the liver or dyslipidemia by studying markers of lipid export (e.g., FABP2-4), both at liver and adipose tissues." (PMID 37125029, 2023).
diabetes (21 papers, 2009 to 2024). "Numerous studies have examined the association between Fabp2 gene polymorphisms and Type 2 diabetes mellitus." (PMID 37221250, 2023). "Many studies have examined the association between the FABP2 (rs1799883) Ala54Thr gene polymorphism and type 2 diabetes mellitus risk (T2DM) in various populations, but their results have been inconsistent." (PMID 25388378, 2014). "In some human groups, the FABP2 was found to have position 54 aa changed from Ala to Thr due to mononucleotide polymorphism (SNP) and this change is associated with diabetes mellitus." (PMID 20140063, 2009). "Specifically, this study assessed whether the Ala54Thr polymorphism of FABP2 modulated changes in glycemic control, serum lipid profiles and body composition values for participants of a three-month diabetes education intervention." (PMID 26703680, 2015). "This study determined whether the Ala54Thr polymorphism of FABP2 affected the blood glucose and lipid parameters of Mexican-Americans with type 2 diabetes using data from a diabetes education program." (PMID 26703680, 2015). "The G-to-A substitution at codon 54 of the FABP2 gene, which results in an alanine-to-threonine substitution at amino acid 54 (Ala54Thr) of I-FABP, has been reported to be associated with increased intestinal fat absorption, as well as FA oxidation, IR, and diabetes." (PMID 33584351, 2021). "FABP2, which is exclusively produced in the small intestine, is a marker of gut permeability and a marker of diabetes-related complications such as nephropathy." (PMID 39114118, 2024). "There were no significant statistical differences in sex, blood pressure, hypertension, diabetes, dyslipidemia, coronary artery disease, stroke, and blood lipid levels in both FABP2 and FABP1 genotypes." (PMID 37091779, 2023). "In the fourth stage of GSE13270 (liver tissue), FABP2, the intestinal fatty-acid-binding protein, is considered a candidate gene for diabetes." (PMID 36141135, 2022). "Duodenal FABP2 gene expression levels, available in a subset of the subjects without diabetes (n = 101), was not influenced by food intake, anthropometric or metabolic parameters." (PMID 32292494, 2020).
Sepsis (19 papers, 2018 to 2025). Sepsis is defined as life-threatening organ dysfunction caused by a dysregulated host response to infection. "In the present study, the levels of plasma D-lactate acid, DAO, FABP2, and FD4 in the sepsis group were significantly elevated than that in the sham group, which indicated that the intestinal mucosal barrier function of sepsis rats was impaired." (PMID 35576220, 2022). "Compared with those in the sham group, the levels of DAO, FABP2, D-lactic acid and FD4 in the sepsis group were significantly increased." (PMID 35576220, 2022). "Moreover, upregulation of HIF-1α after treatment of DMOG cut down the levels of plasma D-lactic acid, DAO, FABP2, and FD-40; while downregualtion of HIF-1α after treatment of BAY 87–2243 aggravated the damage of sepsis to the structure and function of intestinal mucosa." (PMID 35576220, 2022). "Additionally, compared with those in the sepsis group, the levels of DAO, FABP2, D-lactic acid and FD4 in the sepsis + DMOG group were significantly decreased (P < 0.05), however, the levels of DAO, FABP2, D-lactic acid and FD4 in the sepsis + BAY 87–2243 group were increased (P < 0.05)." (PMID 35576220, 2022).